HRNR (hornerin)
Description:
Component of the epidermal cornified cell envelopes.
Synonyms: S100A18; S100A16; FLG3
Tractability: Antibody: its Gene Ontology location is reachable by antibodies, with high confidence.
Target class: Structural protein
Gene: Protein-coding gene on chromosome 1 (152,212,076 to 152,224,193, reverse strand). Ensembl gene ENSG00000197915.
Subcellular location: Cytoplasmic granule
Subcellular location (Human Protein Atlas): Mitochondria
Pathways (Reactome):
Immune System: Neutrophil degranulation
Gene Ontology:
Molecular function: calcium ion binding; transition metal ion binding
Biological process: cell envelope organization; establishment of skin barrier
Cellular component: cornified envelope; cytoplasm; extracellular exosome; extracellular matrix; keratohyalin granule; nucleus; perinuclear region of cytoplasm; azurophil granule lumen; extracellular region
Genetic constraint (gnomAD): Loss-of-function variants: 10 observed, 5.92 expected, observed/expected ratio (o/e) 1.69, 90% interval 0.96 to 1.95. That is too few expected variants to judge how well the gene tolerates losing a copy. Missense variants: 2,828 observed, 1,957.9 expected, observed/expected ratio (o/e) 1.44, 90% interval 1.4 to 1.49. Synonymous variants: 1,006 observed, 795.08 expected, observed/expected ratio (o/e) 1.27, 90% interval 1.2 to 1.33.
Homologues: Orthologues: chimpanzee HRNR (67% identical), mouse Hrnr (41% identical). Paralogues in human: FLG2 (32% identical), FLG (26% identical), RPTN (8% identical).
Diseases named in the same sentence as HRNR in open-access papers:
HRNR is named in the same sentence as 55 diseases in open-access papers, as found by Europe PMC text mining. Sharing a sentence is not in itself a finding about the gene and the disease. The quoted sentences say what the papers report.
atopic dermatitis (9 papers, 2010 to 2025). "One of the variants we studied was SNP (rs877776), located within the region of the HRNR gene-encoding human hornerin, which has been previously identified in the first GWAS of atopic eczema as a novel independent susceptibility locus for this disease." (PMID 36013110, 2022). "HRNR (hornerin) encodes a component of the epidermal cornified cell envelopes, and this gene has been linked with atopic dermatitis (AD) susceptibility in a genome-wide association study." (PMID 23597238, 2013). "HRNR mutations have been associated with atopic dermatitis and other inflammatory dermatoses." (PMID 41488087, 2025). "Finally, the significant association between both risk factors with atopic eczema and eczema-associated asthma prompted us to determine the interactive effects of HRNR and FLG2 SNPs." (PMID 36013110, 2022). "The aim of our current study was to assess the association between the susceptibility to childhood atopic eczema as well as eczema-associated asthma and genetic variants in the HRNR and FLG2 genes, two worthy investigation members of the S-100-fused type protein family, which also includes FLG." (PMID 36013110, 2022). "So far, the HRNR gene was mainly analyzed in the context of the other skin diseases: psoriasis and atopic dermatitis (AD), where barrier defects occur as well, but due to distinct immunogenetic factors." (PMID 37298411, 2023). "For instance, hornerin was found to be downregulated in atopic dermatitis, contributing to the epidermal barrier defect observed in this skin disease." (PMID 37569584, 2023). "We demonstrated that risk variants of HRNR rs877776 [C] and FLG2 rs12568784[T] were associated with atopic eczema, allergic sensitization, and susceptibility to the complex phenotype—asthma plus eczema." (PMID 36013110, 2022). "The presence of both risk factors, at least one HRNR rs877776[C] allele and at least one FLG2 rs12568784 [T] allele, strongly enhanced the risk of atopic eczema." (PMID 36013110, 2022). "Beyond indicating the association of HRNR rs877776 [C] and FLG2 rs12568784[T] with atopic eczema, our study demonstrated that these SNPs are also associated with allergic sensitization and susceptibility to the complex phenotype—asthma plus eczema." (PMID 36013110, 2022). "The aim of this study was to investigate the association of SNPs in hornerin (HRNR) and filaggrin-2 (FLG2) genes with childhood atopic eczema, as well as other atopic phenotypes." (PMID 36013110, 2022). "HRNR, another upregulated gene of OS, has been recently reported to be considered a biomarker for differential diagnosis of atopic dermatitis and expressed in human epidermal keratinocytes." (PMID 34925353, 2021). "Given that the HRNR protein has many structural and functional similarities to FLG, abnormalities in HRNR expression could be involved in the skin barrier dysfunction in atopic eczema." (PMID 36013110, 2022). "Based on these findings, it seems reasonable to assume that genetic variants in HRNR and FLG-2 genes might contribute to the pathogenesis of atopic eczema by possible influence on the gene expression or protein function." (PMID 36013110, 2022). "Genetic variants of filaggrin (FLG) are found in 15–40% of atopic dermatitis patients, and decreased levels of filaggrin and filaggrin-like proteins (hornerin and filaggrin family member 2) are found in lesional and non-lesional skin of atopic dermatitis patients." (PMID 39202657, 2024). "Moreover, we investigated whether an interaction between HRNR and FLG2 SNPs and the four most common FLG mutations affected the atopic eczema risk." (PMID 36013110, 2022). "In conclusion, the present study indicates that risk variants in HRNR and FLG2 genes may contribute to atopic eczema susceptibility; for HRNR SNP, this effect seems to be independent of the well-established FLG risk alleles." (PMID 36013110, 2022).
atopic dermatitis (continued). "In addition, our results reveal that HRNR and FLG2 variants and FLG loss-of-function mutations are candidate genes that might control the risk of atopic eczema in an interactive manner." (PMID 36013110, 2022). "Altogether, the observed association between the rs877776 variant and atopic eczema seems to be very plausible; however, whether this genetic variant could alter the expression or function of the HRNR protein has not yet been investigated." (PMID 36013110, 2022). "Thus, manipulating FLG expression may consequently alter HRNR expression, whereby it should be noted that the latter protein plays a role in atopic dermatitis." (PMID 34572044, 2021). "The same study reported an additional susceptibility SNP located within the hornerin gene (HRNR), which encodes the protein hornerin, on chromosome 1q21, as well as again confirming the association of 4 prevalent FLG null mutations with atopic eczema in a European population." (PMID 20109745, 2010). "Furthermore, the expression levels of HRNR and FLG-2 were shown to be significantly reduced in the skin of patients with atopic eczema, as was also demonstrated for FLG." (PMID 36013110, 2022). "In the current study, we assessed the importance of SNPs in HRNR and FLG2 genes in the susceptibility to childhood atopic eczema and whether this possible association is independent of the FLG risk alleles described previously in this population." (PMID 36013110, 2022).
hepatocellular carcinoma (9 papers, 2018 to 2025). A malignant tumor that arises from hepatocytes. "Hornerin is part of the S100 protein family and was linked to tumor progression in breast cancer and hepatocellular carcinoma." (PMID 41299419, 2025). "Studies have shown that the HRNR gene facilitates hepatocellular carcinoma progression and is associated with a poor prognosis." (PMID 41160379, 2025). "CircCDYL activates mTORC1-p70S6K signaling by stabilizing the hornerin (HRNR) protein and increases the expression of PD-L1 and promotes stemness in hepatocellular carcinoma cells." (PMID 40710359, 2025). "Above all, our data revealed that METTL1-meditated circIPP2A2 promoted malignant behaviors in hepatocellular carcinoma by serving as a scaffold in modulating the Hornerin/PI3K/AKT/GSK3β axis." (PMID 39616161, 2024). "The roles of hornerin in tumor progression or vascularity in several cancers including breast cancer, hepatocellular carcinoma and pancreatic ductal carcinoma have been investigated." (PMID 35246273, 2022). "In the previous study, we identified that Hornerin, a member of the S100 protein family, was overexpressed in patients with hepatocellular carcinoma (HCC), and this upregulation was significantly correlated with poor prognosis." (PMID 39616161, 2024). "The role of HRNR in hepatocellular carcinoma (HCC) progression is investigated in the study." (PMID 30103712, 2018). "Hornerin was recently shown to be highly expressed by pancreatic tumor endothelium; to alter tumor vessel parameters through a VEGF-independent mechanism; and to promote tumor progression in human tissues and in cell models of hepatocellular carcinoma." (PMID 35085295, 2022).
breast carcinoma (8 papers, 2012 to 2025). "Hornerin, a member of the S100 calcium-binding protein family, has been associated with the progression and poor prognosis of hepatocellular and breast cancer." (PMID 32942548, 2020). "The expression levels of HRNR were increased in invasive lobular carcinomas and less aggressive breast carcinoma compared to invasive ductal carcinomas phenotypes." (PMID 30103712, 2018). "It is possible that the fragmentation of hornerin is an important mechanistic step in controlling hornerin action similar to that previously demonstrated in prostate cancer cells or the MCF7 breast cancer cell line." (PMID 22727333, 2012). "Our data show an increase of hornerin expression in invasive luminal breast cancer patient samples compared to invasive ductal carcinomas, and had significant correlation with tumors of a less aggressive pathology." (PMID 22727333, 2012). "Herein, we demonstrate hornerin expression and localization in breast tissue and breast cancer, as well as changes in regulation during cell apoptotic/necrotic events." (PMID 22727333, 2012). "The presence of hornerin in each stage of the MCF10A breast cancer progression model prompted us to investigate hornerin expression in correlation to breast cancer subtype." (PMID 22727333, 2012). "Recent reports have highlighted the importance of the S100 proteins in breast cancer; therefore we further examined the role of hornerin in both normal and cancerous breast tissue." (PMID 22727333, 2012). "Our data opens new possibilities for hornerin and its proteolytic fragments in the control of mammary cell function and breast cancer." (PMID 22727333, 2012). "In the present study we investigated hornerin’s potential role in normal breast cells and breast cancer." (PMID 22727333, 2012). "The expression levels and localization of hornerin in human breast tissue, breast tumor biopsies, primary breast cells and breast cancer cell lines, as well as murine mammary tissue were measured via immunohistochemistry, western blot analysis and PCR." (PMID 22727333, 2012). "It is of note that the MCF10A breast cancer cell line progression model showed increasing amounts of hornerin expression as the tumorigenicity of the cells progressed." (PMID 22727333, 2012). "Given the emerging role of S100 proteins in breast cancer, we investigated hornerin expression in an in vitro breast cancer progression model." (PMID 22727333, 2012). "Breast cancer tissue arrays were analyzed for intensity of hornerin expression via immunohistochemistry." (PMID 22727333, 2012). "Ingenuity pathway analysis (IPA) revealed that the upregulated proteins hornerin (HRNR), tropomyosin alpha-1 chain (TPM1), annexin A (ANXA2), and protein-disulfide isomerase (PDI) were associated with breast or gynecological cancer, breast carcinoma, and inflammation of organ." (PMID 34771120, 2021). "HRNR was reported to be involved in breast cancer development and malignant transformation." (PMID 30103712, 2018). "Furthermore, hornerin expression is decreased in invasive ductal carcinomas compared to invasive lobular carcinomas and less aggressive breast carcinoma phenotypes, and cellular expression of hornerin is altered during induction of apoptosis." (PMID 22727333, 2012). "Furthermore, we show a decrease in hornerin expression in invasive ductal carcinomas compared to invasive lobular carcinomas and less aggressive breast carcinoma phenotypes, and altered cellular expression of hornerin during induction of apoptosis." (PMID 22727333, 2012).
breast carcinoma (continued). "Herein, we demonstrate hornerin expression in human breast tissue and mammary epithelial and stromal cells, its regulation throughout postnatal mammary developmental stages in murine tissue, as well as its expression in correlation with breast cancer subtypes." (PMID 22727333, 2012). "In addition to the breast cancer biopsies, the transcript abundance of hornerin was investigated in a panel of breast cancer cell lines." (PMID 22727333, 2012). "As α2M and CBFA2T2 showed relatively high expression, whilst AHSG and hornerin showed extremely low expression in MDA-MB-231 and MDA-MB-468 cells, we speculated that α2M and CBFA2T2 may play key roles in GALNT6-mediated metastasis of breast cancer." (PMID 32559179, 2020). "Indeed, less hornerin fragmentation is observed in the more aggressive MCF10A lines, similar to less fragmentation observed in the ER/PR negative breast cancer cell lines, which are inherently more invasive and tumorigenic compared to the ER/PR positive cell lines." (PMID 22727333, 2012).
eczema (6 papers, 2010 to 2025). "Next, we restricted the analysis to children with eczema and demonstrated a significant association between HRNR and FLG2 SNPs and allergic sensitization in this subgroup." (PMID 36013110, 2022). "GWAS (genome-wide association study) also revealed that upregulation of HRNR gene is one of the stronger risk factors for eczema, more than for hay fever or asthma." (PMID 34925353, 2021). "A mutation in HRNR, a gene involved in skin barrier function, may be clinically relevant given the patient’s history of eczema." (PMID 41488087, 2025). "In the present study, HRNR and FLG2 risk variants predicted the future development of eczema-associated asthma with a positive predictive value of approximately 50%, which improved considerably when these variants were combined with FLG mutations." (PMID 36013110, 2022). "The exceptions were four variants located on chromosomes 1q21.3 (in/near TCHHL1, HRNR, FLG and SPRR2A) which had significantly stronger effects on age-of-onset of eczema, and one on 17q12 (in GSDMB) which had a stronger effect on the age-of-onset of asthma." (PMID 32603359, 2020). "Four of these had a stronger effect on the age-of-onset of eczema: those in/near HRNR (rs1213821), FLG (rs61816761), TCHHL1 (rs115045402), SPRR2A (rs184587444), all within a 1 Mb locus on chromosome 1q21." (PMID 32603359, 2020). "Recent reports suggested that a single nucleotide polymorphism within the HRNR (hornerin) gene, located 78 kb away from FLG, conferred susceptibility to eczema." (PMID 22403702, 2012). "However, we revealed that the risk alleles HRNR rs877776[C] and FLG2 rs12568784[T], predisposed to eczema-associated asthma, significantly increased the risk of this combined phenotype by nearly four times and more than five-fold, respectively." (PMID 36013110, 2022). "Both risk alleles, HRNR rs877776[C] and FLG2 rs12568784[T], conferred increased risks for asthma in this subgroup, indicating that these SNPs might provide genuine risks for the particular asthma phenotype occurring in the context of eczema." (PMID 36013110, 2022). "In the case of eczema-associated asthma, both HRNR and FLG2 variants alone yielded significantly increased risks; however, the strongest effect was seen in the subjects who combined both at least one HRNR rs877776[C] allele and at least one FLG2 rs12568784 [T]." (PMID 36013110, 2022). "Finally, we investigated whether HRNR rs877776 and FLG2 rs12568784 risk variants can be used as predictive biomarkers for the development of eczema-associated asthma in young children." (PMID 36013110, 2022). "Interestingly, the combination of any tested risk variants, HRNR rs877776[C] or FLG2 rs12568784[T] with FLG mutations, provided the best combination of diagnostic specificity (100%) and predicted eczema plus the asthma phenotype with a positive predictive value of 100%." (PMID 36013110, 2022). "Our results could support this hypothesis as we demonstrated that HRNR and FLG2 risk variants were associated with allergic sensitization even in children without any allergic symptoms, including eczema." (PMID 36013110, 2022). "Interestingly, the effects of HRNR rs877776 and FLG2 rs12568784 risk alleles on allergic sensitization were also independent of concomitant allergic diseases, as the associations were significant in the subgroup of controls without eczema and asthma (OR = 9.04; 95%CI 2.28 ÷ −35.76; p = 0.002)." (PMID 36013110, 2022).
psoriasis (5 papers, 2015 to 2024). An autoimmune condition characterized by red, well-delineated plaques with silvery scales that are usually on the extensor surfaces and scalp. "In a complex manner, these cytokines may be involved in the expression of FLG2 and HRNR and the pathogenesis of psoriasis." (PMID 39624730, 2024). "This study demonstrated that FLG2 and HRNR may play different roles in barrier formation and the pathogenesis of psoriasis." (PMID 39624730, 2024). "Consequently, FLG2 and HRNR may play different roles in barrier formation and the pathogenesis of psoriasis." (PMID 39624730, 2024). "Furthermore, FLG2 and HRNR may play different roles in barrier formation and the pathogenesis of psoriasis." (PMID 39624730, 2024). "Of the five genes (BATF2, HRNR, SIGLEC1, SLC4A11, CXCL10) uniquely identified by multiDE (with Bonferroni adjustment), four were found to be closely related to psoriasis." (PMID 27334001, 2016). "All other DEGPs could be placed along a continuum, with some showing greater psoriasis specificity (e.g., DBI, GLTP, HRNR, KRT73, ELOVL7), and others showing similar expression shifts in many or most skin diseases (e.g., MX1, S100A8, S100A9, STAT1, LAP3)." (PMID 26251673, 2015).
asthma (4 papers, 2020 to 2022). "Mucin-7, Mucin-5B, Immunoglobulin J chain, polymeric immunoglobulin receptor, filaggrin and hornerin were differentially altered in asthma and asthma with chronic rhinosinusitis condition compared to control." (PMID 34414402, 2021). "Interestingly, we confirmed significant associations between both HRNR and FLG2 risk alleles and asthma in this subgroup." (PMID 36013110, 2022).
invasive ductal carcinomas (2 papers, 2012 to 2018). "A total of 125 invasive ductal carcinomas (IDC) and 95 invasive lobular carcinomas (ILC) were analyzed and results showed a significant increase in hornerin expression in the ILC (P < 0.05)." (PMID 22727333, 2012).
melanoma (2 papers, 2020 to 2022). A malignant, usually aggressive tumor composed of atypical, neoplastic melanocytes. "We found that HRNR, KMT2C, and PABPC3 were among the most frequently mutated genes in cutaneous SCCs and melanomas." (PMID 32188867, 2020).
pancreatic ductal adenocarcinoma (2 papers, 2017 to 2022). An infiltrating adenocarcinoma that arises from the epithelial cells of the pancreas. "While confirming hornerin expression in tumor-associated endothelial cells in resected human pancreatic ductal adenocarcinoma (PDAC) samples, it was discovered that hornerin is also expressed in PDAC." (PMID 28916756, 2017).